MYC (MYC proto-oncogene, bHLH transcription factor)
Diseases named in the same sentence as MYC in open-access papers (continued):
Sharing a sentence is not in itself a finding about the gene and the disease.
tumor (continued). "BIN1 has been extensively studied in cancer research and characterized as a tumor suppressor through its interactions with the MYC transcription factor." (PMID 40835006, 2025). "Prior evidence indicates that LIN28B-mediated suppression of let-7 upregulates MYC expression, thereby driving tumor progression in multiple malignancies." (PMID 40740861, 2025). "Tumor ROIs are significantly enriched for MYC targets, oxidative phosphorylation, glycolysis, and fatty acid metabolism, suggesting a highly active metabolic state that supports rapid proliferation and biosynthetic demands." (PMID 40199763, 2025). "In this review, we systematically summarize their involvement in key signaling pathways, including AKT, cell cycle, MYC, ferroptosis and tumor microenvironment." (PMID 41194259, 2025). "These ‘Tumor transition’ cells showed enrichment of ‘glycolysis’ and ‘MYC targets V1’ pathways, which contribute to cell proliferation, growth and metabolism." (PMID 39803458, 2025). "For instance, in the comparison between PCa tumor and normal samples, DiCE identified 61 cancer fitness genes, including MYC, CCNA2, PLK1, PTTG1, EPCAM, and MTOR, that were overlooked by typical DEA but are well-documented contributors to PCa progression." (PMID 40626556, 2025). "High MYC activation correlates with shorter time to first treatment and enhances tumor microenvironment interactions, particularly with myeloid cells." (PMID 40894230, 2025). "MYC acts as a master regulator of cellular proliferation, apoptosis, and tumor progression via interactions with transcription factors and downstream targets." (PMID 40924735, 2025). "MYC, a proto-oncogene, plays a pivotal role in the cell growth and survival processes of cancers, such as tumor metastasis, cell metabolism, and DNA repair." (PMID 40282497, 2025). "Immunohistochemistry (IHC) staining in 20 pairs of HNSCC samples revealed that elevated levels of EZH2 and MYC were present in tumor tissues than adjacent normal tissues." (PMID 39823459, 2025). "Given the well-known function of MYC in the maintenance of both normal and tumor neural stem cells, we decided to investigate MYC protein levels in our model through an immunofluorescence analysis." (PMID 40507925, 2025). "Overall, these findings support the exploitation of CBL0137-mediated MYC downregulation and consequent induction of anti-tumor immunity to improve the treatment of TNBC expressing high levels of MYC." (PMID 39706891, 2025). "Surprisingly, in these studies, preventing MYC dysregulation not only inhibited further tumor development but also led to rapid tumor regression, a phenomenon referred to as oncogene addiction." (PMID 40732268, 2025). "Spatial transcriptomic validation confirmed this spatially structured interaction, with co-localization of mCAFs, HGF, MET, and MYC targets within specific tumor regions." (PMID 41234356, 2025). "SW620 cells, SW620-nkd1−/− cells and SW620-nkd1−/−+MYC cells were subsequently used to construct a xenograft tumor model via subcutaneous injection into the right hind legs of nude mice." (PMID 40675969, 2025). "The MYC oncogene plays a pivotal role in regulating both tumor-suppressive and oncogenic miRNAs, acting as a master transcriptional regulator of a diverse range of miRNAs involved in critical cellular processes." (PMID 40076599, 2025). "For example, in B-cell lymphomas, high c-MYC expression can protect tumor cells from ER stress-induced damage under conditions of proline deprivation." (PMID 41209558, 2025). "Our study reveals that LIN28B drives EC progression through MYC-mediated oncogenesis while concurrently shaping an immunosuppressive tumor microenvironment." (PMID 40740861, 2025).
tumor (continued). "Similarly, MYC is a multifunctional gene that can bind to various cell proliferation and differentiation-associated genes upon overexpression, inhibit, and promote transformation, stimulate transcription, promote metastasis, alter tumor microenvironment, and contribute to increased drug resistance." (PMID 41186627, 2025). "This strategy directly inhibits MYC function at the protein level, reducing MYC-driven tumor growth in vitro and showing preliminary efficacy in xenograft mouse models." (PMID 40365020, 2025). "Collectively, our findings provide the rationale supporting the exploitation of CBL0137-induced anti-tumor immunity in combination with NKG2A blockade to improve the treatment of TNBC expressing high levels of MYC." (PMID 39706891, 2025). "Functioning as a master transcriptional regulator, MYC affects tumor progression by regulating the expression of numerous genes, thereby governing critical biological cascades." (PMID 40740861, 2025). "To access this question, in the current study, we examined TEC subsets in mice with endothelial Notch activation, and found that Notch activation normalized tumor vasculature likely by repressing the proliferating TEC subset via MYC." (PMID 40303332, 2025). "In HGSOC, MYC has been shown to promote several mechanisms that induce oncogenesis and promote cancer progression, including proliferation and tumor cell metabolism." (PMID 39831777, 2025). "Current studies have shown that MYC has an effect on tumor immune response, metabolism, cell cycle, apoptosis, autophagy, pyroptosis, metastasis and angiogenesis." (PMID 41194259, 2025). "Unchecked MYC signaling is oncogenic by orchestrating uncontrolled proliferation and cellular metabolism, impeding tumor-suppressive mechanisms and promoting genomic instability." (PMID 41346415, 2025). "Taken together, these results suggest that I3A treatment inhibited p‐ERK, promoted proteasomal degradation of c‐MYC protein in tumor cells, and increased tumor antigen presentation, thereby increasing T cell activation." (PMID 40583248, 2025). "Sudemycin D6 (SD6), an SF3B1 inhibitor, suppressed colony formation, induced MYC-dependent apoptosis, and inhibited tumor formation and metastasis in MYC-driven TNBC cells." (PMID 39885614, 2025). "These largely disappeared 3 days and 7 days after MYC silencing, a time of marked tumor regression and tissue remodeling and were replaced by a new set of ectopic EC-specific transcripts." (PMID 41008846, 2025). "Longitudinal single‐cell transcriptome analyses of SCLC tumours revealed the role of MYC‐mediated activation of Notch signalling in facilitating the transformation of ASCL1‐positive SCLC to a non‐NE YAP1‐positive state." (PMID 40847555, 2025). "Studies have shown that inhibiting MYC expression has significant anticancer effects in tumor treatment." (PMID 40303931, 2025). "For example, MYC overexpression has been found to facilitate tumor angiogenesis, tumor cell invasion, and metastasis." (PMID 40732268, 2025). "Zhu reported that a MYC-responsive lncRNA called gLINC enhances cancer glycolysis and tumor formation by assembling glycolytic enzymes such as ENO1 and PGK1, PKM2, and LDHA." (PMID 41361062, 2025). "It is encouraging that targeting MYC inhibition has synergized with PD-1 blockade therapy in inhibiting tumor metastasis and recurrence in MYC-positive cells." (PMID 39897587, 2025). "This intervention significantly inhibited tumor growth and enhanced the efficacy of both MYC inhibitors and cisplatin in patient-derived xenograft and transgenic mouse models." (PMID 41409273, 2025). "In tumor cells, the balance between MYC expression and degradation is skewed in favor of expression, leading to accumulation of MYC protein in the cell, its increased stability and hyperactivity." (PMID 39858030, 2025). "This binding enhances MYC mRNA translation, leading to increased glycolysis and tumorigenesis in tumor cells." (PMID 40271153, 2025).
tumor (continued). "Considering that MYC mediates tumor intrinsic malignant properties, as a first step, we aimed at characterizing the biologic effects of CBL0137 in TNBC cells." (PMID 39706891, 2025). "LIN28B exhibits oncogenic roles in EC by facilitating MYC-mediated tumor progression and modulating the immune microenvironment, establishing its potential as both a therapeutic target and a prognostic biomarker." (PMID 40740861, 2025). "After 48 hours, PBMCs produced significantly higher levels of IFNγ and Granzyme B when co-cultured with tumor cells treated with MYC inhibitors." (PMID 40552293, 2025). "Trisomy in chromosome 20 or 8 was associated with the promotion of tumor survival by regulating PLCgamma 1 (PLCG1) and MYC." (PMID 41030949, 2025). "MYC allows tumor cells to evade the immune system on two different levels: First, MYC intracellularly limits the accumulation of stress and damage‐associated molecular patterns and controls the challenges that come along with tumorigenic proliferation." (PMID 40488968, 2025). "In contrast, oncogenic pathways such as MYC targets V2, E2F targets, and the G2M checkpoint were markedly downregulated (p < 0.01), indicating potential tumor-suppressive effects at the transcriptional level." (PMID 40060615, 2025). "It activates the MYC gene via chromosomal translocations and relieves MYC inhibition by sponging miRNAs, thus driving tumor proliferation and survival." (PMID 40703518, 2025). "In a recent study, circPDK1 played a significant role in tumor growth and in promoting glycolysis in vitro and in vivo in a pancreatic subcutaneous tumor mouse model through a MYC-related pathway." (PMID 40126351, 2025). "Combined inhibition of CTPS and ataxia telangiectasia and Rad3-related protein (ATR) exhibits synthetic lethality in MYC-overexpressing cells, promoting cell death in vitro and reducing tumor growth in vivo." (PMID 39852139, 2025). "Inactivating MYC has been shown to inhibit tumor growth and even induce sustained tumor regression across various cancer types, a phenomenon referred to as oncogene addiction." (PMID 40732268, 2025). "This direct transcriptional control by MYC ensures a sustained supply of glycolytic intermediates, fueling both energy production and biosynthetic pathways essential for tumor growth and invasion." (PMID 41234356, 2025). "MYC (the first identified tumor-amplified proto-oncogene) participates in tumor processes and inhibits immune cells when overexpressed." (PMID 41142241, 2025). "The MYC family of oncogenes, including MYC and MYCN, are among the most potent drivers of oncogenesis and are implicated in aggressive tumor subtypes across both pediatric and adult cancers." (PMID 41149606, 2025). "We show that endothelial delivery of MYC siRNA or miR-218 recapitulates Notch activation-induced tumor vessel normalization and remarkably facilitates chemo- and immuno-therapies in mice." (PMID 40303332, 2025). "By monitoring tumor size, we found that the tumor size in the MYC overexpression group at 2 weeks was similar to that in the control groups at 4 weeks." (PMID 39899538, 2025). "For BCSA1, GSVA demonstrated a similar profile between tumor clusters 0, 2, and 6, where high activity in pathways related to proliferation, cell cycle, oxidative phosphorylation, and MYC-targets was observed." (PMID 40925915, 2025). "A recent study reported that a lysine-restricted (LR) diet synergized with MYC inhibition or anti-PD-1 therapy to slow tumor growth." (PMID 40732268, 2025). "In AS, c-MYC overexpression has been observed with varying frequencies depending on the tumor etiology." (PMID 40666093, 2025). "Most importantly, these enable the distinction of VHR tumor groups (canonical MYC and MYCN-amplified SHH) in which all current therapies (conventional chemotherapy and CSI) are ineffective." (PMID 39377358, 2025).
tumor (continued). "MYC, a well‐characterized oncogene, plays a central role in tumor cell proliferation by preventing cell cycle arrest and serves as a critical stemness regulator, maintaining self‐renewal capacity." (PMID 40661135, 2025). "miR-9 activates oncogenic RAS, which induces VEGF expression, and VEGF expression is able to potentiate MYC activity to promote tumor angiogenesis." (PMID 40141375, 2025). "We demonstrate that PA2G4 promotes MYCN-driven tumor growth in vivo and stabilizes c-MYC protein by preventing its proteasomal degradation." (PMID 41002386, 2025). "MYC inhibits cell differentiation and promotes uncontrolled proliferation of tumour cells by preventing their specialization and limiting their ability to proliferate." (PMID 40869000, 2025). "Meantime, I3A induces rapid degradation of c‐MYC in tumor cells and further enhances T cell activation." (PMID 40583248, 2025). "For example, TRMT61A-mediated tRNA-m1A modification regulates the synthesis of MYC protein, thereby influencing tumor cell proliferation." (PMID 40719884, 2025). "Prostate cancer studies revealed that LSD1, along with BRD4 and FOXA1, formed a network enriched in the super enhancer region to regulate MYC expression and influence tumor development." (PMID 39838405, 2025). "To explore this, we conducted a bioinformatics analysis and found that c-MYC is overexpressed at both the gene and protein levels in tumor tissue compared to non-tumor tissue, which impacts patient survival." (PMID 40072116, 2025). "Nanoparticles encapsulated with MYC siRNA (EC-siMYC) or miR-218 (EC-miR-218), a Notch-downstream miRNA suppressing MYC, were able to mitigate Notch inhibition-induced tumor vessel defects." (PMID 40303332, 2025). "Only two drug combinations suppressed proliferation of KRASG12V/MYC tumor cells, namely (R)-GNE-140 in combination with either Metformin or BMS-986205." (PMID 40550880, 2025). "As a transcription factor, c-MYC exerts its oncogenic effects by modulating gene expression programs, both activating and repressing target genes to drive tumor progression." (PMID 40521202, 2025). "It is reported that consistent overexpression of TERC (the RNA component of telomerase) in PCa, driven by MYC, suggests a role in tumor progression." (PMID 41402347, 2025). "Although MYC overexpression contributes to this process, MYC has also been shown to have a well‐established function in masking tumor cells from recognition by the host immune system." (PMID 40488968, 2025). "A study have highlighted, in melanoma nodal metastases, the existence of two distinct subpopulations of cells simultaneously expressing OCT4, SOX2, KLF4, and c-MYC markers—one located in the tumor nests and the other in the peritumoral stroma." (PMID 40806546, 2025). "In metastatic TNBC models, complex 8 reduced the coprecipitation between CCNT1 and CDK9 and decreasedmRNA levels of c-MYC and Mcl-1 in tumor tissues, which suggested thatcomplex 8 disrupted the CDK9–CCNT1 PPI in vivo." (PMID 41152016, 2025). "Efforts to dissociate RNA and DNA-based mechanisms unexpectedly revealed that the PVT1 lncRNA harbors tumor suppressive elements that limit MYC levels." (PMID 40743223, 2025). "MYC silencing on the other hand has the opposite effect, slowing tumor progression, and when performed in combination with MET inhibition, it resensitizes resistant models to TKIs." (PMID 39858062, 2025). "Preclinical studies have shown that combining MDM2 inhibitors with other therapeutic agents, such as chemotherapy or targeted inhibitors of MYC, can synergistically suppress tumor growth and overcome drug resistance." (PMID 40076599, 2025). "It exerts its tumor-suppressive function through multiple pathways, including p16-mediated cell cycle regulation and inhibition of MYC target activation, thereby playing a crucial role in tumor suppression." (PMID 40291911, 2025).
tumor (continued). "MTAR1 recruits IGF2BPs to the PABP1-mediated LLPS complex and enhances the stability and translation of MYC mRNAs, thereby promoting tumor progression." (PMID 40642070, 2025). "The identification of central TFs such as SP1 and MYC, alongside disease‐specific miRNAs like miR‐21 and miR‐34a, underscores the potential of targeting these regulators to disrupt tumor‐promoting pathways." (PMID 40817807, 2025). "For instance, eccDNA carrying amplified oncogenes such as MYC or EGFR contributes to tumor progression, clonal heterogeneity, and resistance to targeted therapies 63,84,85." (PMID 40521196, 2025). "To better align with clinical practice, we extracted MBOs from the fresh tumor tissue of G3 MB patients with MYC amplification." (PMID 40229260, 2025). "Galectin-3 plays a key role in tumor progression and metastasis through c-MYC upregulation and YAP1/RalA/RalBP, conferring an aggressive phenotype." (PMID 40149589, 2025). "While this is a separate limitation of this study pertaining specifically to methylation profiling, the fact that this particular tumor clustered to the MYC-activated subtype of AT/RT is significant as RMC is particularly enriched for MYC." (PMID 39833894, 2025). "Using integrated bioinformatics analysis of TCGA/GTEx datasets and functional validation in EC cell models, we investigate the molecular interplay between LIN28B and MYC and evaluate its impact on tumor immune microenvironment reconfiguration." (PMID 40740861, 2025). "Recent studies have shown that MYC can promote an immunosuppressive tumor microenvironment in multiple human cancers and MYC overexpression correlated with low immune cell infiltration in TNBC patients." (PMID 39706891, 2025). "The analysis of tumor-associated transcripts showed that both M1 and M2 conditioned medium induced high levels of EPCAM mRNA and significantly decreased the expression of MYC, an epithelial-to-mesenchymal transition marker, in SCC cell lines." (PMID 41259557, 2025). "We found that C3 represents the initial stage of GBM evolution, resembling normal tissues and exhibiting low levels of DNA repair, oxidative phosphorylation, and MYC targets, indicating tumour immaturity and potential transformation to C2 and C4 subtypes." (PMID 41292185, 2025). "Further investigation revealed that macrophages upregulate the expression of the long noncoding RNA, Linc01559, in DA through the STAT3/c-MYC signaling pathway, thereby promoting malignant phenotypes such as invasion, metastasis, tumor stemness, and apoptosis." (PMID 40722682, 2025). "GSEA revealed significant enrichment of OXPHOS and MYC target pathways in C1_Scissor+ relative to C2_Scissor– malignant cells, suggesting a possible synergistic role in driving tumor progression." (PMID 40642093, 2025). "Based on the signal intensity, numerous tumor cells appeared to be proliferatively expanding upon MYC reactivation." (PMID 39934876, 2025). "Mechanistically, we reveal that the knockdown of antizyme inhibitor 1 (AZIN1) or suppression of polyamine production reduces MYC expression, leading to diminished tumor cell viability via the downregulation of cell cycle-related genes." (PMID 40246846, 2025). "We removed and photographed the subcutaneous tumors from nude mice and found that knocking out the NKD1 gene resulted in a significant reduction in tumor volume, whereas overexpression of MYC in SW620-nkd1−/− cells markedly increased the tumor volume." (PMID 40675969, 2025). "Very interestingly, a MYC dominant negative peptide, Omomyc, has shown remarkable anti‐cancer properties in a wide range of tumor types and now is starting to be applied in clinical practice." (PMID 40955778, 2025).